SASH3 (SAM and SH3 domain containing 3)
Diseases named in the same sentence as SASH3 in open-access papers (continued):
Sharing a sentence is not in itself a finding about the gene and the disease.
cancer (continued). "Given the effects of SASH3 on diverse human cancer immune cell infiltration, we can infer that increased expression of SASH3 may promote mast cell infiltration and contribute to a poor prognosis." (PMID 35756681, 2022). "ROC curve analysis showed that SASH3 could be used as a biomarker to diagnose different types of cancer with high sensitivity and specificity." (PMID 35756681, 2022). "Results confirmed that SASH3 could be used as a biomarker to diagnose different types of cancer with high sensitivity and specificity." (PMID 35756681, 2022). "Additionally, we discovered that SASH3 expression was associated with prognosis, diagnosis, TMB, MSI, and infiltration levels of immunosuppressive cells in pan-cancer." (PMID 35756681, 2022). "Kaplan–Meier analysis utilized the prognostic values of SASH3 in diverse cancers." (PMID 35756681, 2022). "Interestingly, SASH3 methylation was correlated with the prognosis of cancer patients, and we found that in KIRC and UVM, the high DNA methylation level of SASH3 was correlated with better OS, and associated with poor OS in SKCM." (PMID 35756681, 2022). "The results of this study confirmed that SASH3 plays a critical role in cancer prognosis and may serve as an important prognostic and diagnostic biomarker." (PMID 35756681, 2022). "Moreover, we identified genes with positive coexpression with SASH3 using the TCGA database, and the heatmap showed the top 100 genes that are positively correlated with SASH3 in pan-cancer (r > 0.6, p < 0.0001)." (PMID 35756681, 2022). "In view of the clinical significance of SASH3 across different cancer types, we also examined whether SASH3 could be used as a potential biomarker for the early diagnosis of human cancers." (PMID 35756681, 2022). "In this study, we first analyzed SASH3 expression in diverse cancer." (PMID 35756681, 2022). "Next, we investigated whether SASH3 could act as a biomarker for different cancer types." (PMID 35756681, 2022). "The results detailed above suggested that SASH3 may have roles in cancer progression." (PMID 35756681, 2022). "Therefore, our results demonstrated that SASH3 might affect immune cell infiltration, making them a predictive biomarker for immunotherapy in cancer patients." (PMID 35756681, 2022). "Currently, there is still no research that examines whether SASH3 is correlated with a cancer prognosis or can be a prognostic and diagnostic biomarker for human cancer." (PMID 35756681, 2022). "However, the immunological function of SASH3 in pan-cancer is insufficient." (PMID 35756681, 2022). "First, although we explored the correlation between SASH3 and immune infiltration in pan-cancer patients, there is a lack of experiments to validate the function of SASH3 in the TME regulation of diverse cancer." (PMID 35756681, 2022). "To investigate the protein level of SASH3 in human cancer, we used UALCAN database analysis and proved that SASH3 was highly expressed in BRCA, KIRC, PAAD, HNSC, and GBM." (PMID 35756681, 2022). "We explored the correlation between SASH3 expression and MSI in human cancers." (PMID 35756681, 2022). "We examined the correlation between SASH3 expression and TMB of human cancers." (PMID 35756681, 2022). "Currently, there are still no studies that examine whether SASH3 is correlated with cancer progression." (PMID 35756681, 2022).
immune disorder (2 papers, 2022 to 2025). "Src Homology 3 Domain-containing Adaptor Protein 3 (SASH3) deficiency is an X-linked immune disorder." (PMID 40947476, 2025).
SASH3 also shares sentences with these, for which no sentence is quoted: Immunodeficiency (2 papers); cholangiocarcinoma (1); colon adenocarcinoma (1); colon cancer (1); diverticulosis (1); esophageal carcinoma (1); gastric cancer (1); glioma (1); inflammatory bowel disease (1); liver cancer (1); lung squamous cell carcinoma (1); Metaphyseal dysplasia (1); osteogenesis imperfecta (1); Pan (1); Primary immunodeficiency (1); psoriasis (1); rectum adenocarcinoma (1); rheumatoid arthritis (1); toxoplasmosis (1); type 1 diabetes mellitus (1).